RBX1 (ring-box 1)
Diseases named in the same sentence as RBX1 in open-access papers (continued):
Sharing a sentence is not in itself a finding about the gene and the disease.
cancer (continued). "Gain-of-function mutations in NFE2L2, loss-of-function mutations in key members of the KEAP1/CUL3/RBX1 E3-ubiquitin ligase complex, and succination of KEAP1 have proven to activate the NRF2 pathway in many cancer types." (PMID 36068196, 2022). "Several studies have shown that RBX1 is participated in different aspects of the cancer biology, and lots of RBX1 molecular functions are in accordance with its function in cancer." (PMID 35802537, 2022). "While genetic alterations or misregulation of the individual F-box proteins are associated with genomic instability and cancer pathogenesis, less is known about the tumorigenic roles of the invariable SCF components SKP1, CUL1, and RBX1." (PMID 34445249, 2021). "In contrast, downregulation of RBX1 expression triggers multiple death and growth arrest pathways to effectively suppress the malignant phenotypes of cancer cells." (PMID 33504946, 2021). "RBX1 is overexpressed in multiple cancers, thus to modulate the proliferation of gastric cancer cells." (PMID 35006464, 2021). "Altogether, targeting overexpressed Prame in cancer cells inactivated RBX1-Cullin2-EloB-Prame E3 ligase (CRL2Prame) and halted p14/ARF degradation to restrain tumor growth by inducing G2/M phase cell cycle arrest." (PMID 33504946, 2021). "Similar to the CUL7 scaffold proteins, the catalytic components Rbx1 and Skp1 are also regarded as an oncoprotein in most of the cancers." (PMID 33130829, 2020). "An increase of Nrf2 pathway activation, resulting from the disruption of KEAP1/CUL3/RBX1 E3-ubiquitin ligase complex is observed in many cancers and potentially leads to chemoresistance." (PMID 32346533, 2020). "The disruption of this partnership involving the ubiquitination of NFE2L2 through the KEAP1/CUL3/RBX1 complex and its posterior proteasomal degradation, which leads to the constitutive activation of antioxidant response genes is known in several cancer types." (PMID 26792175, 2016). "In addition, among the TCGA‐MM patients, high expressions of either FEN1, RBX1, and COX8A were significantly associated with poor overall survival and cancer‐specific survival." (PMID 39206872, 2024). "Along with epigenetic modifiers that were previously implicated in cancer cell fitness, such as CHD1, CHD4, DNMT3B, ELP3, SUPT16H, SUV39H2; novel hits ASH2L, RBX1 and SSRP1 were discovered as essential genes for both U373 and T98G cells suggesting common regulatory role." (PMID 37974198, 2023). "UBA3, UBE2M and RBX1 are important for the proliferation and apoptosis of cancer cells." (PMID 35880551, 2022). "Meanwhile, the overall expression level of RBX2 was higher than that of RBX1 in pan-cancer." (PMID 36059474, 2022). "Using bioinformatics methods, we elucidated the immunological role of the Ring finger family across cancers and provided in first time the gene expression and genetic alteration of RBX1/2 in the regulation of different immune components including their association with PD-L1 expression." (PMID 36059474, 2022). "In conclusion, different expression patterns of RBX1/2 in various cancer types may lead to different characterization of tumors." (PMID 36059474, 2022). "However, there were a few apparent exceptions in the 18 types of cancers, a lower RBX1 expression was detected in KICH compare to the matches normal tissues, whereas RBX2 was under expressed in COAD and READ in addition to KICH." (PMID 36059474, 2022). "Similarly, the NEDD8 E3 ligases, DCN1 and RBX1/2, are also up-regulated in several types of human cancer types." (PMID 35880551, 2022). "We summarized RBX1/2 CNV landscape in 33 cancer types by using the GSCA database, respectively." (PMID 36059474, 2022). "Previous genetic studies have shown that heterozygous knockout of SKP1, CUL1, RBX1 and FBXO7 induces CIN, an enabling hallmark of cancer frequently associated with cellular transformation, drug resistance, metastasis and poor patient prognosis in many cancer types." (PMID 35008511, 2021).
cancer (continued). "Interestingly, when shallow deletions or gains of SKP1, CUL1, and RBX1 are assessed concurrently within three commonly diagnosed cancers, there is a compounding effect." (PMID 34445249, 2021). "Additionally, cursory analyses revealed that the core SCF complex member genes typically harbor fewer than 20 mutations within a given cancer type (right), with specific genes, namely SKP1 and RBX1 having fewer than 10 mutations in each cancer type." (PMID 35008511, 2021). "P14/ARF was significantly accumulated upon RBX1 downregulation in all tested cancer cell lines." (PMID 33504946, 2021). "However, there have been limited studies in genetically engineered animal models, and the mechanistic function of Rbx1 in different cancers remains to be elucidated." (PMID 33130829, 2020). "In addition, the Rbx1, Hdac2, and Pik3r2 are involved in the signaling pathway of cancer cells." (PMID 35468821, 2022). "Thus, specific inhibitors preventing the binding of CUL7 with Rbx1 may be a novel therapeutic option for suppressing CUL7-related cancers." (PMID 33130829, 2020). "The role of RBX1 in mouse development and in regulation of cancer cell survival was unknown." (PMID 19660140, 2009). "Most of these genes were cell cycle-related genes, including CHEK1, CDK1, RUVBL2, PSMD14, SUPT5H, RBX1, and AURKA, across 28 cancer types." (PMID 38972884, 2024). "These include the tumour suppressors, PDCD4, RB1, STK2, transcriptional regulators with reported roles in cancer, BCL9L, STAT5B and proteins that are involved in control of the cell cycle, ANAPC4, ANAPC5, RBX1." (PMID 35573784, 2022). "The highest heterozygous amplification ratio (45.71%) for RBX1 was found in LUSC, whereas the heterozygous amplification ratio of RBX2 presented a higher level of state in several cancers (>50%) including CESC, HNSC, LUSC and OV." (PMID 36059474, 2022). "To explore the effect of RBX1/2 on the overall picture of SCF complex and in the tumor evolution, we comprehensively analyzed their difference in pan-cancer using the TCGA database in the present study." (PMID 36059474, 2022). "Our analyses showed that RBX1 expression in the immune subtypes of BLCA, UCEC and UVM had no statistical significance, while RBX2 expression in above three cancers was closely related with those immune subtypes." (PMID 36059474, 2022). "To gain a pan-cancer perspective on alterations to these genes, we evaluated the DNA CN status of VHL, CUL2, RBX1, ELOC, and ELOB across 33 cancer types processed by TCGA." (PMID 35664333, 2022). "For instance, CUL2, RBX1, ELOB, and ELOC are known to interact with PRAME, a substrate-recognition subunit that is overexpressed in a variety of cancers, including HCC." (PMID 35664333, 2022). "The expression of RBX1 was in connection with the infiltration of B cell, CD4+ T cells and neutrophils in above four cancers." (PMID 36059474, 2022). "Next, CNA analyses revealed that each gene is frequently altered in 10 common cancer types, and that SKP1, RBX1, FBXW7 and FBXO5 tend to exhibit more losses, while CUL1 and SKP2 exhibit more gains." (PMID 35008511, 2021). "SCF complex is mainly comprised of RBX1, SKP1, CUL1 and F-box protein family, whose dysregulation is highly related with cancer progression." (PMID 35006464, 2021). "RBX1/ROC1 disruption results in early embryonic lethality, cancer cell death or the inhibition of tumor cell migration." (PMID 28418860, 2017). "In non-luminal HER2-positive cancer high LFNG expression and low RBX1 expression was associated with worse OS." (PMID 41463075, 2025). "RBX1 also shows upregulation in all cell lines, particularly in HSF, T-47D, and U-937, indicating enhanced proteasomal degradation and possibly contributing to cancer cell death." (PMID 39805861, 2025). "Furthermore, we demonstrated that RBX1 knockdown increased the levels of the Twist family bHLH transcription factor 1 (TWIST1), is a significant regulator in the EMT process in some cancers." (PMID 35802537, 2022).
cancer (continued). "Second, the knockdown of RBX1 remarkably raised the FBXO45 protein level, but the expression of FBXO45 mRNA was not affected in TNBC cancer cells with RBX1 knockdown." (PMID 35802537, 2022). "For further identifying whether RBX1 could modulate the expression of TWIST1, we first looked at the mRNA and protein levels of TWIST1 in overexpressed or RBX1 knockdown TNBC cancer cells." (PMID 35802537, 2022). "RBX1 is highly expressed in ESCC and promotes the growth of cancer cells." (PMID 34281459, 2021). "To gain novel insight into cancer pathogenesis, we determined the prevalence of genetic and epigenetic alterations in six prototypic SCF complex member genes (SKP1, CUL1, RBX1, SKP2, FBXW7 and FBXO5) from patient datasets extracted from The Cancer Genome Atlas (TCGA)." (PMID 35008511, 2021). "In addition to proteins known to directly bind REN, such as Cul3, RBX1, and KCTD15, we recovered various potential REN interactors including SALL4, a cell stemness regulator aberrantly activated in several types of human cancers." (PMID 38062245, 2024). "However, RBX1 had no significant relation with the prognosis in above cancers." (PMID 36059474, 2022). "Interestingly, RBX1 and SKP2 tend to be hypomethylated across all cancer types, irrespective of copy number status, whereas FBXW7 is differentially methylated across cancer types." (PMID 35008511, 2021).
tumor (37 papers, 2009 to 2026). "The overexpression of RBX1 was evidently associated with the lymph node metastasis together with tumor stage." (PMID 35802537, 2022). "Collectively, these findings support the possibility that SKP1, CUL1, and RBX1 encode tumor suppressor- or oncogene-like activities depending on whether they are under- or over-expressed." (PMID 34445249, 2021). "Furthermore, although a few proteins associated with tumor growth have been identified as substrates of the RHOBTB2-Cul3/Rbx1 complex, the exact mechanisms by which RHOBTB2 functions as a tumor suppressor remain unclear." (PMID 39736890, 2024). "RBX1 is a component of the VHL tumor suppressor complex, which ubiquitinates HIFα subunits (HIF1α, HIF2α, and HIF3α) and targets them for degradation under normoxic conditions." (PMID 40436847, 2025). "We conducted an in-depth investigation to understand the effects of RBX1 on the metastasis of ATC by constructing the tumor models in nude mice, which were classified into shRBX1 and shNC groups." (PMID 36810109, 2023). "Overall, these in vitro and in vivo experiments indicated that RBX1 functions as a tumor promoter and stimulates tumor cell growth." (PMID 37639640, 2023). "Upon Rbx1‐deletion, these growth‐promoting effect was abrogated, leading to suppression of tumor progression and extension of mouse life‐span." (PMID 37470067, 2023). "RBX1 is E3 ubiquitin ligase and its repression attenuates tumor proliferation through cell cycle arrest, programmed cell death and senescence." (PMID 37974198, 2023). "PKM2 is a type of functional downstream target of RBX1 in modulating aerobic glycolysis, which is essential for RBX1-mediated tumor progression." (PMID 36810109, 2023). "High levels of RBX1 were strongly related to tumor metastasis and short overall survival in ATC patients." (PMID 36810109, 2023). "In this study, our data reflected that the expression of RBX1 was higher in tumors of ATC patients when compared with that in the relevant non-tumor tissues." (PMID 36810109, 2023). "First, we observed that PKM2 is a type of functional downstream target of RBX1 in modulating aerobic glycolysis, which is essential for RBX1-mediated tumor progression." (PMID 36810109, 2023). "The model of metastatic tumour was established by tail vein injection in nude mice, we further explored the influence of RBX1 against TNBC metastasis." (PMID 35802537, 2022). "Next, we determined the TWIST1 protein level in 30 RBX1 up-regulated TNBC tumour tissues using western blotting." (PMID 35802537, 2022). "Subsequently, qRT-PCR was employed for determining RBX1 expression in 30 TNBC patients together with the non-tumor adjacent tissues." (PMID 35802537, 2022). "In accordance with the raised RBX1 mRNA level, the RBX1 protein level was evidently higher in the TNBC tissues in contrast to non-tumor adjacent tissues." (PMID 35802537, 2022). "RBX1/2 expression showed their own specific characteristics in tumor pathological stages and grades, copy number variation and immune components." (PMID 36059474, 2022). "What’s more, in patients with TNBC, the overexpression of RBX1 was remarkedly related to overall survival, lymph node metastasis stage together with tumour stage." (PMID 35802537, 2022). "The RBX1 protein levels in non-tumor adjacent tissues together with TNBC tissue samples were examined through immunohistochemical approach." (PMID 35802537, 2022). "Future animal study will be required to evaluate the anti-tumor effect by targeting DDX11-AS1/miR-514b-3p/RBX1 axis in ESCA tumorigenesis." (PMID 34281459, 2021). "In hepatocellular carcinoma, RBX1 promotes tumor cell growth and the development of cell malignant phenotypes." (PMID 34281459, 2021). "In this study, proteomic analysis of RBX1-interacting proteins revealed p14/ARF, a well-known tumor suppressor, as a novel ubiquitin target of RBX1." (PMID 33504946, 2021).
tumor (continued). "RBX1 was reported to be over-expressed in human tumor tissues, and was suggested to contribute to tumor progression and poor prognosis by regulating cell proliferation, apoptosis and senescence." (PMID 31562368, 2020). "Our analysis on individual complex component genes revealed that, in addition to different frequencies of disruption, each tumor type displays a distinctive pattern of CUL3/KEAP1/RBX1 E3-ubiquitin ligase complex alterations." (PMID 25114896, 2014). "2009; 106:6203-6208Jia L, Soengas MS, Sun Y. ROC1/RBX1 E3 ubiquitin ligase silencing suppresses tumor cell growth via sequential induction of G2-M arrest, apoptosis, and senescence." (PMID 19660140, 2009). "RBX1 facilitated tumor metastasis via regulation of FBXO45-TWIST1-dependent degradation in TNBC." (PMID 38773471, 2024). "Thus, the combined inhibition of RNAP2 and RBX1 suppresses tumor cell growth synergistically, improving the efficiency of the RNAP2 inhibitor conjugated antibody." (PMID 38407310, 2024). "Overall, these in vitro and in vivo experiments indicated that the RBX1-p27 axis could be a central molecular mechanism by which RBX1 functions as a tumor promoter and stimulates cell growth in chemotherapeutic drugs treated MM cells." (PMID 37639640, 2023). "Furthermore, RBX1 reduction increased the number of cleaved-caspase-3 positive apoptotic tumor cells compared with the vehicle treatment cells." (PMID 37639640, 2023). "To investigate whether tumor suppression by Rbx1 deletion can be reflected by an extension in mouse life‐span, we determined the mouse survival after Ad‐Cre administration." (PMID 37470067, 2023). "Moreover, the xenograft tumor growth curve showed that the tumor with RBX1 silencing grew much more slowly than the control cells." (PMID 37639640, 2023). "Thus, tumor growth inhibition by Rbx1‐deletion is also likely attributable to accumulation of cell cycle inhibitor p21 and apoptosis inducer Foxo1, but not p27 and Nrf2." (PMID 37470067, 2023). "We then conducted a rescue experiment to determine whether RBX1 accelerates tumour invasion and metastasis in an FBXO45-TWIST1-dependent manner." (PMID 35802537, 2022). "In addition, RBX1 as a part of ROC1/RBX1 E3 ubiquitin ligase silencing inhibited tumor cell growth via sequential induction of G2/M arrest, apoptosis, and induction of senescence." (PMID 36476410, 2022). "In the current work, our outcomes exhibited that the expression levels of RBX1 were raised in the tumours of TNBC patients in contrast to the associated non-tumour tissues." (PMID 35802537, 2022). "Accumulating evidence has revealed that RBX1 is highly expressed in many types tumor cells." (PMID 34281459, 2021). "In non-muscle invasive bladder cancers (NMIBCs), RBX1 is an independent prognostic marker, which is closely associated with tumor size, stage and patient survival." (PMID 34281459, 2021). "However, the frequency of alterations affecting RBX1 in OVCA was the highest of any complex component gene in any of the tumor types analyzed, with CNL of RBX1 observed in 81.5% of 568 cases." (PMID 25114896, 2014). "Taken together, the potential implications of DNA-level alterations affecting components of the CUL3/KEAP1/RBX1 protein complex are broad and, cumulatively, may have profound implications in tumor biology." (PMID 25114896, 2014). "In addition, a recent study demonstrated that a novel circular RNA DIDO1 could specifically bind to PRDX2 and promote its ubiquitination and degradation in a RBX1-dependent way, which inhibited its downstream signaling pathways to suppress tumor progression." (PMID 35813474, 2022). "Furthermore, several studies revealed that miRNA or lncRNA targeting Rbx1 could regulate tumor growth, invasion, migration, and metastasis, including miR-194, miR-378, miR-1827, and lncRNA LUCAT176,78,80." (PMID 33130829, 2020). "Functional assays demonstrated that silencing RBX1 markedly inhibited PAAD cell proliferation and tumor growth both in vitro and in xenograft models." (PMID 41899625, 2026).
tumor (continued). "As the Warburg effect is characterized by a metabolic shift that is ubiquitous in the tumor cells, involving ATC, we investigated the effect of RBX1 on the glucose metabolism in ATC." (PMID 36810109, 2023). "In conclusion, our studies demonstrate that NLRP6 acts as a scaffold protein to interact with p85α and recruit RBX1 to ubiquitinate p85α for OPTN-mediated autophagic degradation, leading to PI3K/AKT activation to enhance tumour progression." (PMID 37770465, 2023). "Here, we demonstrated that NLRP6 acts as a scaffold protein to interact with p85α and recruit RBX1 to ubiquitinate p85α for OPTN-mediated autophagic degradation, leading to PI3K/AKT activation to enhance tumour progression." (PMID 37770465, 2023). "Previous studies have shown that miR‐194 inhibited tumor progression by downregulating FOXM1, RBX1, and KDM5B." (PMID 33605558, 2021). "We evaluated the frequency of CUL3, RBX1, and KEAP1 disruption across multiple tumor types from the TCGA, selected based on data availability from TCGA (Section 2)." (PMID 25114896, 2014). "For example, Ring-Box 1 (RBX1) which is tumor-essential in both CRISPR and RNAi screening, indicated pan-essentiality in tumor cell lines, and genomic alteration of RBX1 may possibly reduce cell viability." (PMID 37845222, 2023). "Conversely, RBX1 overexpression remarkably raised the TWIST1 protein level in the TNBC cells, whereas the TWIST1 mRNA expression was not affected in RBX1 knockdown or overexpression in TNBC tumour cells." (PMID 35802537, 2022). "RBX1 mRNA was overexpressed in tumor samples compared with their non-neoplastic counterparts." (PMID 36810109, 2023). "Indeed, IHC staining showed that the levels of p21 and Foxo1, two tumor suppressors were increased substantially, whereas the levels of p27 and Nrf2 were not elevated in Rbx1‐null tumor tissues." (PMID 37470067, 2023). "Interestingly, RBX1 had a protective role in OV (P=0.002), PCPG (P=0.014), suggesting RBX1 may exert tumor suppressor effect in OV and PCPG." (PMID 36059474, 2022). "The difference between RBX1 and RBX2 may lead to different tumor outcomes." (PMID 36059474, 2022). "Further analysis revealed that there were significant difference of Ring finger genes expression comparing primary tumor to adjacent normal tissues, for example, RBX2 expression in COAD tissues was lower than adjacent non-COAD tissues, while RBX1 was in the opposite situation." (PMID 36059474, 2022).